TXNIP (thioredoxin interacting protein)
Diseases named in the same sentence as TXNIP in open-access papers (continued):
Sharing a sentence is not in itself a finding about the gene and the disease.
tumor (continued). "Our study provides the first evidence that increased TXNIP induces aggressive tumor behaviors in HCC cells by increasing cellular ROS level, motility and invasion." (PMID 30627326, 2018). "Thioredoxin interacting protein (TXNIP) is a novel tumor suppressor that is down‐regulated in several cancer tissues and tumor cell lines." (PMID 30410860, 2018). "TXNIP has previously been shown to act as both a tumor suppressor and as an oncogene, depending on the context." (PMID 30479697, 2018). "The up-regulation of TXNIP expression and subsequent induction of apoptosis have also been shown to be the mechanism of the anti-tumor effect by various agents such as anisomycin, oxidative stress, dexamethasone, PPARγ, calcium influx and potassium ion." (PMID 28029659, 2017). "The expression level of TXNIP was also examined by IHC in RNF2 knockdown DU145 xenograft tumor tissues, and results showed that RNF2 knockdown group had increased TXNIP level than the control group." (PMID 28029659, 2017). "Of the 150 tumor tissues, 48 cases (32%) and 102 cases (68%) expressed TXNIP at high and low levels, respectively." (PMID 25605021, 2015). "We next analyzed the correlation between TXNIP, p27 and Her-2 expression at the tumor microarray or at tumor tissues, respectively." (PMID 25605021, 2015). "TXNIP has been shown to be an important tumor suppressor, and its expression is dramatically reduced in various types of human tumors." (PMID 26019137, 2015). "VEGFA, PKIB and TMPRSS2 were increased by FGF23 stimulation in LNCaP cells while the tumor suppressor TXNIP was decreased." (PMID 26019137, 2015). "TXNIP is a known binding partner and inhibitor of the cellular antioxidant and tumor promoter thioredoxin (Trx)." (PMID 24645981, 2014). "TXNIP is highly upregulated when PPARγ, which we have previously shown to be a tumor promoter, is depleted from ATC cells." (PMID 24645981, 2014). "TXNIP overexpression in the T238 cell line resulted in attenuated bioluminescence compared to vector control, and resultant tumor volumes were significantly smaller." (PMID 24645981, 2014). "Metastatic tumor burden was significantly reduced in the mice injected with TXNIP-overexpressing T238 cells compared to vector controls." (PMID 24645981, 2014). "TXNIP has been shown to be a tumor suppressor in other cell types, and our results here show for the first time that it serves a similar function in thyroid cells." (PMID 24645981, 2014). "TXNIP can reduce tumor invasion and angiogenesis through inhibition of thioredoxin and can directly impact cell survival by promoting a pro-apoptotic environment." (PMID 24645981, 2014). "TXNIP has many biological functions, including the inhibition of tumor growth, suppression of hepatocarcinogenesis, and regulation of glucose metabolism and ROS generation in different cell types." (PMID 24098117, 2013). "MK-801 dephosphorylated Thr24 in FOXO1 and induced its nuclear translocation, thus increasing transcription of TXNIP, a tumor suppressor gene." (PMID 24112473, 2013). "Its expression is down-regulated in many tumor cells and overexpression of TXNIP inhibits cancer cell growth." (PMID 24112473, 2013). "TXNIP has many biological functions, including the inhibition of tumor growth, suppression of hepatocarcinogenesis, and regulation of glucose metabolism and reactive oxygen species (ROS) generation in different cell types." (PMID 24098117, 2013). "Suppression of FOXO down-regulates target genes, including Bim, FasL and TXNIP, a tumor suppressor gene, whereas overexpression of FOXO1 enhances TXNIP promoter activity." (PMID 24112473, 2013).
tumor (continued). "It is also consistent with the known role of TXNIP as a probable tumor suppressor in several cancer types where it has been shown to suppress oncogenic phenotypes and its loss of function linked with cancer development." (PMID 20844768, 2010). "Previous studies have suggested that TXNIP serves as a negative regulator of glucose metabolism in tumor cells; however, its role in CD8+ T cell glucose metabolism remains unclear." (PMID 40346484, 2025). "By modulating the antioxidant systems, cellular metabolism, and the remodeling of extracellular matrix, TXNIP exerts tumor suppressive activities in various human cancers such as colorectal, liver, breast, and lung carcinomas and hematologic malignancies, including AML." (PMID 39364720, 2025). "Initially, TXNIP overexpression in HCC-1954 cells inhibited tumor growth as expected." (PMID 40175348, 2025). "In summary, TXNIP emerges in our work as a significant factor for tumor response to ADT." (PMID 41213907, 2025). "Notably, all tumor relapse samples after ADT therapy exhibited very low TXNIP levels, indicating that low levels of TXNIP are needed for tumor recurrence; however, TXNIP levels pre-therapy did not forecast therapy response, although a trend was observed." (PMID 41213907, 2025). "Conversely, TXNIP could suppress tumor growth by upregulating IL-24 and downregulating p-STAT3 signaling." (PMID 40175348, 2025). "Among the identified genes, TXNIP, a tumor suppressor, was greatly induced by JQ1." (PMID 41249136, 2025). "TXNIP knockdown increased MDA-MB-231 tumor growth and metastasis." (PMID 40175348, 2025). "To identify TXNIP-associated proteins that might regulate tumor growth and survival, we performed co-IP followed by mass spectrometry in TXNIP-KD MDA-MB-231 cells and TXNIP-OE HCC-1954 cells." (PMID 40175348, 2025). "Moreover, univariate analysis revealed that low TXNIP expression, tumor numbers >1, poor tumor differentiation, and microvascular invasion were risk factors for OS in patients with HCC (red dots)." (PMID 40008893, 2025). "TXNIP expression in tumor cells is well documented but its role remains controversial." (PMID 40260243, 2025). "TXNIP knockdown significantly increased MDA-MB-231 tumor growth." (PMID 40175348, 2025). "This decrease in TXNIP gene expression level in tumor was also observed within each CD4+ T cell subtype, indicating that this decrease not only results from changes in main cell subtypes composition but also from intrinsic transcriptomic adaptation to tumor micro-environment." (PMID 40260243, 2025). "Additionally, under oxidative stress induced by the tumor microenvironment, thioredoxin-interacting protein (TXNIP) interacts with the NLRP3 inflammasome, leading to IL-1β maturation and secretion, which correlates with postoperative RCC recurrence." (PMID 40718836, 2025). "Altogether, studying single cell transcriptomic data generated from patients’ tumor, we observed that TXNIP could have a potential role in T cell activation within the TME." (PMID 40260243, 2025). "We confirmed TXNIP downregulation in tumor infiltrating T cells in cancer patients." (PMID 40260243, 2025). "Additionally, TXNIP, a coagulation-modulating gene, was downregulated after TTFields exposure, indicating a link to immune regulation in the tumor microenvironment." (PMID 40885689, 2025). "In this context, TXNIP, a known tumor suppressor, is often downregulated in CC." (PMID 40665897, 2025). "Furthermore, the oe-NCL + oe-MYC + oe-TXNIP group showed a significant increase in tumor volume and ki67-positive cell ratio compared to the oe-NCL + oe-MYC + oe-NC group." (PMID 40346484, 2025). "TXNIP has been characterized as a tumor suppressor in multiple types of cancers." (PMID 38920655, 2024). "Moreover, TXNIP knockdown suppressed the effects of Dpep on glucose uptake and glycolysis and, significantly, on tumor cell survival, but again, only in lines in which it was upregulated by the peptide." (PMID 38920655, 2024).
tumor (continued). "As demonstrated by cellular experiments, miR-106b could upregulate with the advancing MF stage and repress the tumor inhibitors TXNIP and cyclin-dependent kinase inhibitor p21, promoting MF tumor cell growth." (PMID 39256366, 2024). "Similarly, our in vivoexperiments confirmed that TXNIP overexpression suppresses tumor cell proliferation andrestricts tumor growth." (PMID 38229544, 2024). "Interestingly, this study showed a significantly positive correlation between TXNIP expression and inefficient vascularisation favouring tumor cell survival in RCC." (PMID 37794178, 2023). "TXNIP has also been reported to reduce the migratory capacity of tumor cells." (PMID 37794178, 2023). "Additionally, a reduction in TXNIP induced by M2 macrophage-derived exosomes has been observed to be critical for maintaining cancer “stemness” and promoting tumor progression in HCC." (PMID 37794178, 2023). "With a renewed emphasis on therapies which modulate the tumor metabolome, these and additional TXNIP agonists may show great potential." (PMID 37794178, 2023). "The regulation of TXNIP expression, therefore, appears to be under the control of a plethora of inter-cellular signals (multiple cytokines and exosomal miRNAs), which makes it complex to establish the exact role of TXNIP in tumor microenvironment-driven tumor progression." (PMID 37794178, 2023). "In the related tumor section, the proliferation marker Ki-67 is increased after TXNIP suppression." (PMID 37095099, 2023). "TXNIP is classified as a tumor suppressor and its basal expression is frequently lost in cancer." (PMID 36860653, 2023). "However in tumor cells, TXNIP suppresses TNF-α-induced NF-κB activity and subsequently inhibits hepatocarcinogenesis." (PMID 37794178, 2023). "In addition to being a major redox regulator, TXNIP has also been identified as a tumor suppressor gene (TSG), and its expression is reduced in a wide range of primary tumors and cancer cell lines compared to normal tissue and cell lines, respectively." (PMID 37794178, 2023). "Like LUM, TXNIP was abundant but downregulated in the analyzed tumor samples." (PMID 36982287, 2023). "Furthermore, we determined TXNIP tumor suppressive function in the CML cell lines by lentivirus expressing TXNIP shRNA." (PMID 37095099, 2023). "Quantification of apoptosis-related proteins Bax, bcl-2, and proliferation-related protein Ki67 in xenograft tumor sections showed that TXNIP upregulation could promote the apoptosis of DOX-induced drug-resistant cells and inhibit their proliferation in vivo." (PMID 35414060, 2022). "In addition, based on the analyses of the immune and matrix scores, immune checkpoints, and tumor neoantigen, we obtained the specific immunologic landscape of TXNIP in different tumors." (PMID 35843949, 2022). "The immune system’s ability to recognize and destroy tumor cells may be controlled by TXNIP’s immunological modulatory properties." (PMID 36366411, 2022). "All in all, TXNIP plays an important role in tumorigenesis and tumor immunity, and may be a potential prognostic and therapeutic biomarker." (PMID 35843949, 2022). "TXNIP, a metabolic protein, has been considered to be a tumor suppressor gene in various malignant tumors, and its overexpression can suppress the growth and metastasis of cancer cells in tumor transplant models." (PMID 36418919, 2022). "Transcriptome clustering research showed that TXNIP is related to tumor chemotherapy resistance." (PMID 35414060, 2022). "TXNIP is a tumor suppressor whose expression is reduced in various human cancers." (PMID 36366411, 2022). "Results of the KEGG enrichment analysis suggested that “ubiquitin mediated proteolysis” ranked first among those enriched pathways, suggesting that it may be related to the role of TXNIP in tumor pathogenesis." (PMID 35843949, 2022). "In addition, TXNIP has broad functions in energy metabolism, insulin sensitivity, and tumor suppressor activity in various cancer cells." (PMID 35429141, 2022).
tumor (continued). "Additionally, the expression of TXNIP in cancer is low and TXNIP overexpression inhibits the proliferation of cancer cells; therefore, it is regarded as a potential tumor suppressor." (PMID 36059548, 2022). "The immune system’s ability to recognize and destroy tumor cells may be controlled by the immunological modulatory properties of TXNIP." (PMID 36366411, 2022). "TXNIP plays a tumor inhibitory role as an apoptosis inducer; thus, TXNIP agonists may contribute to anticancer treatment." (PMID 36059548, 2022). "Importantly, the role of TXNIP in carcinogenesis and modulating tumor progression has been attracting increasing interest." (PMID 35843949, 2022). "Therefore, TXNIP is thought to play a role in tumor suppression by impeding cellular glucose uptake, disrupting the cell cycle, and increasing oxidative stress." (PMID 36366411, 2022). "According to other studies investigating the role of PTPs proteins in many diseases, TXNIP activation may act as a tumor suppressor or an oncogene." (PMID 36366411, 2022). "Since the re-introduction of TXNIP successfully rescued the glucose metabolism promoting the effect of Ct-HBx, we further characterized whether it could arrest tumor cells growth." (PMID 33323975, 2021). "By integrated analysis of HCC patients from the TCGA database and our clinical cohort, we demonstrated that TXNIP is a potent tumor suppressor gene in HBV-induced HCC, and truncated HBx could downregulate the expression of TXNIP." (PMID 33323975, 2021). "The miR-135b-5p inhibition weakened tumor growth and increased the expression of TXNIP reversely." (PMID 34277424, 2021). "Based on these data TXNIP was suggested to be a tumour suppressor gene." (PMID 34433833, 2021). "Based on our results that IL1β expressed preferentially in a group of tumours showing strong TXNIP nuclear expression in supporting endothelial cells indicates that the IL1β expression is mediated through the NFkB pathway, rather than direct activation of NLRP3 inflammasome." (PMID 34433833, 2021). "By contrast, TXNIP being a participant of apoptosis inducer and metabolic re-programmer works as a tumor suppressor; therefore, downregulation of TXNIP contributes to cancer progression, although such anticancer functions of TXNIP are associated to apoptotic pathways." (PMID 33803178, 2021). "Around small necrotic tumour areas tumour cells displayed strong cytoplasmic TXNIP immunoreaction." (PMID 34433833, 2021). "In conclusion, we confirmed the C-terminal truncation of X gene is a tumor-specific event during the viral integration process in the human genome and proposed a novel gene: TXNIP as a tumor suppressor gene in HBV-induced HCC by transcriptome sequencing and profiling." (PMID 33323975, 2021). "Interestingly, higher TXNIP expression levels in On-treatment specimens positively correlated with higher degree of tumor regression (RECIST, Response Evaluation Criteria in Solid Tumors; linear model, P = 0.00898)." (PMID 33846376, 2021). "And the inhibition of miR-135b-5p/TXNIP axis might be a promising strategy to increase the anti-tumor effect of DDP." (PMID 34277424, 2021). "However, only the expression of TXNIP, not CYP2J2 or GPC3, was positively correlated with the expression of circDCUN1D4 in LUAD tumor tissues, confirming that TXNIP is the target of circDCUN1D4." (PMID 33425493, 2021). "MiR-135b-5p/TXNIP pathway contributes to the anti-tumor effect of DDP." (PMID 34277424, 2021). "The degradation of TXNIP was reported to increase glycolysis to promote tumor cell migration." (PMID 33425493, 2021). "On protein level TXNIP expression increased in both tumor lines after 24 h." (PMID 33407762, 2021).
tumor (continued). "Also, it should be noted that suppressing the activity of MondoA-TXNIP can facilitate Th17 inflammation and stimulate CD8+ T cell exhaustion, indicating the roles of TXNIP in regulating tumor microenvironment." (PMID 34484334, 2021). "However, decreases of TXNIP in advancing lesions is consistent with its putative tumor suppressor function, as forced expression inhibits malignant proliferation in CTCL-derived cell lines." (PMID 34583709, 2021). "Therefore, we detected TXNIP protein expression immunohistochemically in a large multi-tumor tissue microarray (TMA)." (PMID 33081035, 2020). "The inhibition of TXNIP promotes tumor cell proliferation, EMT, and metastasis." (PMID 33228209, 2020). "Thus, the downregulation of TXNIP is frequent in tumor cells, and some of the mechanisms by which that is accomplished include targeting the TXNIP N-terminus, affecting the TXNIP promoter, or binding to the 3′-untranslated region (3′-UTR) of TXNIP." (PMID 33228209, 2020). "Given the fact that the morbidity and mortality of cancer in China are continuously rising, seriously threatening people's lives, the prospect of regulating the levels of TXNIP by either genetic means or through drug development gives hope that new tumor treatments can be found." (PMID 33194655, 2020). "Further, TXNIP might display immune activation in a tumor site and may aid in predicting response to modern immune therapy." (PMID 33081035, 2020). "The levels of TxNIP expression also differed between different tumour types (P = 0.017)." (PMID 32418115, 2020). "Subsequently, TXNIP expression might be used to monitor the functional state of tumor-infiltrating leukocytes in tissue sections and may help to predict response to modern immune therapy." (PMID 33081035, 2020). "Studies have indicated that TXNIP overexpression can decrease tumor growth in mice." (PMID 33194655, 2020). "TXNIP is expressed at low levels in a variety of malignancies and the overexpression of TXNIP inhibits the proliferation of cancer cells, and so it can be considered as a potential tumor suppressor gene." (PMID 33194655, 2020). "Immune modulatory functions of TXNIP might control immune recognition and elimination of tumor cells." (PMID 33081035, 2020). "Given the bifunctional nature of TXNIP and the diverse functions it can execute in tumorigenesis, its expression might differ dependent on tumor origin and tumor subtype." (PMID 33081035, 2020). "Furthermore, metabolic and oxidative stress as well as hypoxia or hyperglycemia can promote TXNIP expression, which is also considered as a tumor suppressor." (PMID 33228209, 2020). "Furthermore, we investigated TXNIP staining of immunocompetent cells in the proximity of the xenograft tumor tissue." (PMID 33081035, 2020). "In conclusion, this study suggests that TXNIP downregulation is as a common feature in human tumor xenograft models and provides new insights into TXNIP expression on the protein level in various tumor entities." (PMID 33081035, 2020). "However, in recent years, TXNIP gained attention in tumor biology as well as the redox state of a cell critically affects induction of apoptotic pathways." (PMID 33081035, 2020). "The micro RNA miR-411-5p/3p is significantly upregulated in human NSCLC tissues and cell lines, and the overexpression of miR-411-5p/3p can inhibit the expression of SPRY4 and TXNIP, which in turn promote tumor proliferation and migration, preventing apoptosis in NSCLC cell lines." (PMID 33194655, 2020). "Furthermore, we analyzed TXNIP expression in widely used tumor cell lines taken directly from 2D-culture and in archival mouse xenograft tumor tissues." (PMID 33081035, 2020). "As an important tumor repressive gene, TXNIP expression induced by NaBu is TRAF6‐dependent." (PMID 31578830, 2020). "High expression of both cytoplasmic Trx and TxNIP was also associated with the absence of tumour recurrence (χ2 = 5.663, df = 1, P = 0.029 and χ2 = 6.147, df = 1, P = 0.013, respectively)." (PMID 32418115, 2020).